GFAP (glial fibrillary acidic protein)
Diseases named in the same sentence as GFAP in open-access papers (continued):
Sharing a sentence is not in itself a finding about the gene and the disease.
Hyperammonemia (5 papers, 2016 to 2024). An increased concentration of ammonia in the blood. "In hyperammonemic rats the GFAP-stained area increased to 42 ± 0.5% (p < 0.0001) compared to 25 ± 2% in control rats, indicating astrocyte activation in hyperammonemia." (PMID 38671534, 2024). "To assess the effects of hyperammonemia on the IL-17 receptor in microglia and astrocytes we performed double immunofluorescences of IL-17 receptor with Iba1 (marker of microglia) or GFAP, marker of astrocytes." (PMID 38671534, 2024). "Hyperammonemia also increased the activation of astrocytes, reflected in an increase in the area covered by the anti-GFAP staining (23 ± 1.6%; p < 0.05) compared to the control rats (16 ± 1.2), while JTE-013 reversed the astrocytes activation (12 ± 4.3%, p < 0.01)." (PMID 38139078, 2023). "To investigate whether hyperammonemia leads to neuroinflammation and neurodegeneration, we labeled reactive astrocytes with GFAP and degenerating neurons using Fluoro-Jade C staining." (PMID 35427648, 2022). "The total amount of GFAP, as analyzed by Western blot, was not affected by hyperammonemia or SFN treatment." (PMID 27090509, 2016). "The number and area of glial fibrillary acidic protein (GFAP)-positive reactive astrocytes was increased following 1 h NH4Cl injection, while the number of Iba1-positive microglia was not modified, suggesting that acute hyperammonemia induced by this agent leads to astrocytic neuroinflammation." (PMID 35427648, 2022).
hyperlipidemia (5 papers, 2014 to 2025). "Immunohistochemistry, real-time PCR, and immunoblotting were performed to evaluate GFAP levels for understanding the mechanism of neuronal damage caused by hyperlipidemia." (PMID 34409103, 2021). "To investigate the pathological changes in hyperlipidemia-induced neuroinflammation, we performed GFAP immunohistochemical staining of different brain tissues (cerebral cortex, hippocampal CA1 area, hippocampal CA3 area, and dentate gyrus)." (PMID 34409103, 2021). "We found increased MCP-1, CD11b and GFAP immunoreactivity in hypercholesterolemic ischemic brains, suggesting that MCP-1 production and microglia and astrocyte activation are involved in the promotion of hyperlipidemia-induced inflammation and injury in the ischemic brain." (PMID 25017431, 2014).
Insulin resistance (5 papers, 2017 to 2025). Increased resistance towards insulin, that is, diminished effectiveness of insulin in reducing blood glucose levels. "Notably, we found significant positive correlations between plasma GFAP levels and C-peptide at baseline, as well as insulin and insulin resistance, after 3 months in our study." (PMID 39275164, 2024). "Interestingly, we have also shown that inhibition of mitochondrial fission in GFAP-expressing astrocytes of the DVC has an important protective effect on the development of HFD-dependent insulin resistance." (PMID 33227495, 2021). "This analysis revealed unaltered GFAP protein expression between both groups indicating that the observed insulin resistance is not paralleled by astrocyte reactivity." (PMID 33946318, 2021).
necrotizing enterocolitis (5 papers, 2019 to 2022). Necrotizing enterocolitis (NEC) is a devastating disease that affects mostly the intestine of premature infants. "In addition, MCC950 administration also reduced the necrotizing-enterocolitis-enhanced Iba-1- and GFAP-positive cells in both the hippocampus and cerebral cortex." (PMID 35219323, 2022). "During chronic tissue inflammation, significantly increased expression of GFAP on glial cells after stimulation with LPS and pro-inflammatory cytokines has been shown, similar to what has been seen in Crohn's disease (CD) and necrotizing enterocolitis (NEC)." (PMID 31736937, 2019).
neural tumors (5 papers, 2014 to 2024). "To determine the origin of TDECs in primary patient GBM (p-GBM), we first co-stained for ETV2 with neural stem-like cell markers (Nestin, Vimentin, and CD133) or mature neural tumor cell makers (NeuN and GFAP) in cryosections of p-GBM autopsies." (PMID 29527330, 2018).
neurofibroma (5 papers, 2021 to 2025). An intraneural or extraneural neoplasm arising from nerve tissues and neural sheaths. "These neurofibromas exhibited classic diffuse-type histologic morphology and expected patterns of S100, SOX10, GFAP, and CD34 immunohistochemistry." (PMID 37817770, 2023).
neuropathic pain (5 papers, 2019 to 2025). Chronic pain caused by damage to nerve fibers. "In a neuropathic pain model, EA markedly decreased GFAP expression in the amygdala, relieved neuropathic pain, and reduced comorbid negative behavior." (PMID 40890793, 2025). "Consequently, the expression of P2X3 and P2X4 is overtly increased in DRGs, as evidenced by high levels of P2X3 and incremental co-expression of P2X4 and GFAP in this finding, and their suppressions relieve mechanical hyperalgesia in neuropathic pain animal models." (PMID 37533160, 2023). "In our study, PTP1B‐IN‐1 administration effectively suppressed the elevated Iba‐1, GFAP, TNF‐α, IL‐6, and IL‐1β in SNI‐induced neuropathic pain rats." (PMID 38334011, 2024).
Optic neuropathy (5 papers, 2022 to 2025). "The results of multivariate logistic regression analysis showed that serum ATX, GFAP, and NfL levels were independent risk factors for optic neuropathy in DR patients (P < 0.05), and GFAP and NfL were independent protective factors (P = 0.001)." (PMID 40520775, 2025). "Five patients (16%) in the GFAP‐astrocytopathy group presented with optic neuropathy related to optic disc edema." (PMID 40581835, 2025). "The limited sample size, however, restricts our ability to draw firm conclusions about the clinical utility of sNfL and GFAP as biomarkers of neurodegeneration in these optic neuropathies." (PMID 41357352, 2025). "We also observed increased plasma levels of sNfL and GFAP in both groups, supporting the presence of ongoing neurodegeneration in both optic neuropathies." (PMID 41357352, 2025). "For animals in the traumatic optic neuropathy cohort, we confirmed injury site in longitudinal nerve sections by immunolabelling against GFAP, counterstaining nuclei with DAPI and tracking RGC active uptake and anterograde transport of CTB." (PMID 36267329, 2022).
pituicytoma (5 papers, 2011 to 2025). An extremely rare, WHO grade I, circumscribed and slow-growing tumor that arises from the neurohypophysis or infundibulum and described in adults. "Immunohistochemical staining showed that S-100 was strongly positive, GFAP was invisible or weakly positive, EMA was rarely positive, and TTF-1 positivity was helpful for the diagnosis of pituicytoma." (PMID 34210357, 2021). "In general, all pituicytomas showed diffuse nuclear labeling for TTF-1 and positive expression of EMA, S100 and GFAP to varying degrees." (PMID 34210357, 2021). "Generally, pituicytomas are noninfiltrative and immunoreactive for vimentin, S-100 protein, and GFAP (often focally), with occasional cytoplasmic EMA positivity." (PMID 26962837, 2016). "The distinction from pituicytoma relies on the evidence of oncocytic change in SCO rather than GFAP staining patterns alone." (PMID 21320334, 2011). "SCOs generally do not express glial fibrillary acidic protein (GFAP), distinguishing them from pituicytoma, a tumor derived from neurohypophyseal glial pituicytes." (PMID 27175596, 2016).
pituitary adenomas (5 papers, 2012 to 2021). "In our studies, only 8% of all the pituitary adenomas showed evidence of GFAP and cytokeratin co-expressing cells." (PMID 33001343, 2021). "This present retrospective study was undertaken to investigate the expression of intermediate filaments GFAP and cytokeratin in pituitary adenoma with relation to hormone expression and clinical parameters." (PMID 33001343, 2021). "Cellular co-expression of the intermediate filaments GFAP and cytokeratin in pituitary adenomas and the pituitary was demonstrated and shown to be associated with hormone expression and low recurrence rate." (PMID 33001343, 2021). "Evaluation of the 326 pituitary adenomas revealed 62 cases (19%) with co-expression of GFAP and cytokeratin." (PMID 33001343, 2021). "Simultaneous co-expression of GFAP and cytokeratin in the same cells was demonstrated in 26 out of 326 pituitary adenomas and in all 13 pituitaries." (PMID 33001343, 2021). "Against this background, it would be of interest to further investigate whether pituitary adenomas with GFAP cytokeratin co-expressing cells express NGF receptors and/or if they represent increasing neural elements upon the influence of IGF-1." (PMID 33001343, 2021). "The significant correlation between the expression of EG-VEGF and the expression of GFAP and S100 protein could imply the action of this growth factor on follicular-stellate cells from the normal human pituitary gland and from the pituitary adenomas." (PMID 28386275, 2017). "GFAP expression can be activated by tumor stem cells of pituitary adenomas." (PMID 22574128, 2012). "However, we could prove for the first time the simultaneous cellular co-expression of the intermediate filaments GFAP and cytokeratin in pituitary adenomas as well as in pituitary anterior lobes." (PMID 33001343, 2021). "The statistically significant correlation found between the expression of EG-VEGF and the expression of GFAP and S100 protein suggests a possible role of EG-VEGF in the reactivity of follicular-stellate cells in pituitary adenomas." (PMID 28386275, 2017). "However, as GFAP has not been detected within these neural cells of pituitary adenomas, they seem to be not identical to the ones we observed here." (PMID 33001343, 2021).
prostate carcinoma (5 papers, 2021 to 2025). A carcinoma that arises from epithelial cells of the prostate gland. "Among these, Glial Fibrillary Acidic Protein (GFAP) plays a critical role in forming complex fibrous networks and is implicated in cellular signaling, intercellular communication, and cell migration processes, making it a potential biomarker for prostate cancer." (PMID 40228435, 2025).
sarcopenia (5 papers, 2023 to 2026). Progressive decline in muscle mass due to aging which results in decreased functional capacity of muscles. "When stratifying for age and sex, p‐tau181 and GFAP emerged as the markers significantly associated with sarcopenia incidence in individuals over 78 years old and in males." (PMID 40490961, 2025). "ApoE4 status and plasma p-tau217 (AD), NfL (neurodegeneration), GFAP and IL-6 (inflammation), GDF-15 (senescence/sarcopenia) will be evaluated in all subjects (n = 1,662) both at the baseline and at the end of the study (12 months)." (PMID 40400914, 2025).
systemic lupus erythematosus (5 papers, 2021 to 2025). An autoimmune multi-organ disease typically associated with vasculopathy and autoantibody production. "Studies have found that curcumin inhibits the increase of matrix protein, glial fibrillary acidic protein, and vimentin in the hippocampus of lupus mice." (PMID 34557547, 2021).
temporal lobe epilepsy (5 papers, 2018 to 2025). A localization-related (focal) form of epilepsy characterized by recurrent seizures that arise from foci within the temporal lobe, most commonly from its mesial aspect. "In drug-resistant temporal lobe epilepsy associated with FCD, adults exhibit higher GFAP/S100/caspase-3, while children show more vimentin, with region-dependent patterns." (PMID 41155206, 2025). "Witcher & Ellis addressed a paradox in temporal lobe epilepsy, of increased GFAP and decreased glutamate transporter EAAT2, which is predominantly expressed in astroglial cells and throughout the astrocytic membrane." (PMID 29634780, 2018).
Tinnitus (5 papers, 2022 to 2025). Tinnitus is an auditory perception that can be described as the experience of sound, in the ear or in the head, in the absence of external acoustic stimulation. "The top2 key proteins GFAP and S100B indicate the importance of astrocytes in the remodeling of the IC complex in tinnitus." (PMID 40076458, 2025). "The database analysis carried out in the present study links changes in the interactions of BDNF-NTF3-NTRK3 in IC in tinnitus with altered interactions between astrocytes (GFAP, S100B) and neurons." (PMID 40076458, 2025). "The genes that were down-regulated in the tinnitus group, were influenced by more than just an outlier value, and had corresponding FC values of >1 included GFAP (logFC= −3.04), APLNR (−2.95), PREX2 (−1.44), and PLVAP (−1.04; all p < 0.01)." (PMID 37048724, 2023). "In a salicylate model of tinnitus, increased GFAP and Iba-1 expression was reported in the primary AC and in the MGB." (PMID 36009087, 2022). "The detection of GFAP and S100B as the top2 key proteins in tinnitus is unexpected." (PMID 40076458, 2025). "Notably, in the tinnitus rats induced by salicylate, a marked increase in GFAP expression is observed in the auditory cortex, accompanied by increased endpoint and process length of astrocyte." (PMID 37592237, 2023). "Interestingly, the MGB assumes a critical role in tinnitus pathology, and GFAP expression has been shown to remain stable in the rat tinnitus model compared to the auditory cortex." (PMID 37240833, 2023).
tuberculosis (5 papers, 2023 to 2025). A chronic, recurrent infection caused by the bacterium Mycobacterium tuberculosis. "Some GFAP antibody-associated disorder patients also have low CSF glucose, necessitating differentiation from CNS infections, particularly tuberculosis." (PMID 41333477, 2025). "Patient 8, who had a radiculopathy and was initially seen by infectious disease specialists, benefited from a full-length anti-tuberculosis treatment, even though the PCR and specific culture were negative, and despite the fact that GFAP-Abs-related disease was retained as the final diagnosis." (PMID 37540278, 2023).
tuberculosis meningitis (5 papers, 2018 to 2025). "This study aimed to summarize the clinical features of Autoimmune Glial Fibrillary Acidic Protein Astrocytosis mimicking tuberculosis meningitis to improve clinicians’ understanding of this disease." (PMID 37338614, 2023). "GFAP and the albumin index were significantly higher in bacterial and tuberculosis meningitis groups, whereas total tau was elevated in the Japanese encephalitis virus infection group." (PMID 33115334, 2021).
X-linked adrenoleukodystrophy (5 papers, 2020 to 2025). X-linked adrenoleukodystrophy (X-ALD) is a peroxisomal disorder resulting in cerebral demyelination, axonal dysfunction in the spinal cord leading to spastic paraplegia, adrenal insufficiency and in some cases testicular insufficiency. "Changes in CSF and blood levels of GFAP and NfL have also been observed in X-linked adrenoleukodystrophy." (PMID 38558318, 2024). "Our study illustrates the potential of plasma NfL as biomarker of spinal cord degeneration in adrenoleukodystrophy, which was superior to plasma GFAP in our cohort." (PMID 33047897, 2020).
AIDS (4 papers, 2016 to 2025). A syndrome resulting from the acquired deficiency of cellular immunity caused by the human immunodeficiency virus (HIV). "In inflammatory foci with mononuclear nodules in the subcortical cerebellar white matter, GFAP+ astrocytes were reduced in SIV/+AIDS." (PMID 27737697, 2016). "Similarly, the astrocytes of the subcortical white matter were also activated and showed upregulated GFAP expression in SIV/+AIDS." (PMID 27737697, 2016).
amnesia (4 papers, 2021 to 2025). Pathologic partial or complete loss of the ability to recall past experiences ( AMNESIA, RETROGRADE) or to form new memories ( AMNESIA, ANTEROGRADE). "We aimed to determine whether transient global amnesia (TGA) is associated with alterations in central nervous system (CNS) injury biomarkers—serum neurofilament light chain (sNfL) and serum glial fibrillary acidic protein (sGFAP)." (PMID 40141275, 2025).
anemia (4 papers, 2023 to 2026). A reduction in the number of red blood cells, the amount of hemoglobin, and/or the volume of packed red blood cells. "Men in the anemia/sensory impairment and the cardiometabolic/inflammatory patterns had generally higher levels of p‐tau181, p‐tau 218, t‐tau, NfL, and GFAP compared to men in the unspecific pattern." (PMID 40545553, 2025). "GFAP levels were elevated in children <5 years of age compared with older children in cerebral malaria (P = 0.02) and community children (P = 0.004) but not severe malarial anaemia (P = 0.31)." (PMID 38075948, 2023).
Batten disease (4 papers, 2014 to 2022). "Furthermore, the loss of GFAP and vimentin in a mouse model for chronic neurodegenerative Batten disease impairs the blood-brain barrier and accelerates the onset and progression of the pathology." (PMID 30186118, 2018). "Notably, these bands of reactive GFAP-positive Bergmann glia correlated directly with areas of Purkinje cell degeneration and loss, a pattern also seen in the brains of humans and mice with other lysosomal storage disorders, such as Juvenile neuronal ceroid lipofuscinosis." (PMID 25314316, 2014). "Interestingly, this is in contrast to increased presence and/or reactivity of microglia that we previously reported in GFAP-/-Vim-/- mice that were crossed with the Batten disease mouse model." (PMID 29401502, 2018).
chordoma (4 papers, 2008 to 2025). Chordomas are rare malignant tumors arising from embryonic remnants of the notochord in axial skeleton. "MPE with clear cell changes and positive staining for S-100 protein, keratins and EMA can be misdiagnosed as chordoma, the latter being positive for Cytokeratin markers and S-100 protein but negative for GFAP." (PMID 18928567, 2008).
cortical atrophy (4 papers, 2024 to 2026). "In this regard, magnetic resonance imaging (MRI) markers like cortical atrophy, spinal cord atrophy and paramagnetic rim lesions (PRL) as well as serum-biomarkers like glial fibrillary acidic protein (GFAP) were shown to be associated with higher PIRA risk." (PMID 40495080, 2025). "In the APOE ε4ε4 group, higher global cortical atrophy score correlated with higher serum NfL (Rho = 0.78, p < 0.001) and higher plasma GFAP concentrations (Rho = 0.53, p = 0.024)." (PMID 38762725, 2024).
developmental delay (4 papers, 2014 to 2023). "A de novo GFAP missense variant was identified in a child presenting with hypotonia, developmental delay, and abnormal brain MRI." (PMID 27648269, 2016). "A de novo GFAP variant, p.R376W, was identified in a child presenting with hypotonia, developmental delay, and abnormal brain MRI." (PMID 27648269, 2016). "As our patient presented with developmental delay, hypotonia, and abnormal brain MRI, with no signs of regression, it could not confidently be concluded that the identified GFAP variant was associated with his disease phenotype." (PMID 27648269, 2016).
endotoxemia (4 papers, 2011 to 2018). "In GFAP/IL-17A mice, LPS-induced endotoxemia led to a more pronounced microglial activation with expansion of a distinct CD45high/CD11b+ population and increased induction of proinflammatory cytokines compared with controls." (PMID 23468966, 2013). "With dioscin treatment, the number of GFAP immuno-reactive astrocyte decreased greatly, indicating that dioscin may have a potential role in the regulation of neuro-inflammation and treatment of endotoxemia induced acute neuro-inflammation." (PMID 28059131, 2017). "We next examined whether markers for iron handling, the transferrin receptor (TFR-1) and astrocyte (GFAP) and microglial (IBA-1) activation were altered by LPS-induced endotoxemia." (PMID 21943033, 2011).